SLITRK6 (SLIT and NTRK like family member 6)
Description:
Regulator of neurite outgrowth required for normal hearing and vision.
Synonyms: FLJ22774; DFNMYP
Tractability: Antibody: UniProt places it where antibodies can reach, with high confidence; its Gene Ontology location is reachable by antibodies, with high confidence; UniProt predicts a signal peptide or a membrane-spanning region; the Human Protein Atlas places it where antibodies can reach.
Gene: Protein-coding gene on chromosome 13 (85,792,790 to 85,806,683, reverse strand). Ensembl gene ENSG00000184564.
Subcellular location: Cell membrane
Subcellular location (Human Protein Atlas): Plasma membrane
Pathways (Reactome):
Neuronal System: Receptor-type tyrosine-protein phosphatases
Gene Ontology:
Biological process: synapse assembly; axonogenesis; positive regulation of synapse assembly
Cellular component: cell surface; plasma membrane; cell periphery
Genetic constraint (gnomAD): Loss-of-function variants: 35 observed, 57.17 expected, observed/expected ratio (o/e) 0.61, 90% interval 0.47 to 0.81. The upper end of that interval is the gene's LOEUF score, 0.81, which puts it in group 3 of 6, group 1 being the genes least tolerant of losing a copy. Missense variants: 977 observed, 1,037.2 expected, observed/expected ratio (o/e) 0.94, 90% interval 0.89 to 0.99. Synonymous variants: 392 observed, 380.91 expected, observed/expected ratio (o/e) 1.03, 90% interval 0.95 to 1.12.
Gene-disease validity (ClinGen):
ClinGen rates the evidence that SLITRK6 causes each of these diseases.
high myopia-sensorineural deafness syndrome (autosomal recessive): Definitive. High myopia-sensorineural deafness syndrome is a rare genetic disease characterized by high myopia, typically ranging from -6.0 to -11.0 diopters, and moderate to profound, bilateral, progressive sensorineural hearing loss with prelingual-onset.
Homologues: Orthologues: chimpanzee SLITRK6 (99% identical), macaque SLITRK6 (98% identical), pig SLITRK6 (92% identical), mouse Slitrk6 (89% identical), rabbit SLITRK6 (89% identical), rat Slitrk6 (88% identical), tropical clawed frog slitrk6 (61% identical), zebrafish slitrk6 (52% identical). Paralogues in human: SLITRK4 (41% identical), SLITRK5 (40% identical), SLITRK2 (39% identical), SLITRK3 (38% identical), SLITRK1 (31% identical), SLIT1 (18% identical), SLIT3 (17% identical), SLIT2 (17% identical), TLR9 (16% identical), GP5 (15% identical), LRRN1 (14% identical), LINGO2 (14% identical), and 13 more.
Diseases named in the same sentence as SLITRK6 in open-access papers:
SLITRK6 is named in the same sentence as 28 diseases in open-access papers, as found by Europe PMC text mining. Sharing a sentence is not in itself a finding about the gene and the disease. The quoted sentences say what the papers report.
breast carcinoma (4 papers, 2018 to 2025). "According to Kaplan–Meier plotter, low expression of NHS, THBS4, and SLITRK6 is associated with poor relapse-free survival (RFS) in breast cancer patients." (PMID 32679794, 2020).
hearing loss (4 papers, 2011 to 2024). "Considering that significant associations exist between sensorineural hearing loss and balance disorders, it is possible that SLITRK6 is involved in some pathophysiological processes of pediatric vestibular disorders." (PMID 21298075, 2011). "In GER (CD−M3), Tecta, Pcdh15, and Cdc14a were associated with NSHL, Slitrk6 with deafness and myopia, Pcdh15 with Usher syndrome, Eya1 with branchiootorenal syndrome, Chd7 with CHARGE syndrome, and Cdc14a with hearing impairment and infertile male syndrome." (PMID 39684410, 2024). "In the SLITRK6 gene (OMIM609681, NM_032229.2), the variant c.1240C>T, p.(Gln414*) in the homozygous state was detected in a patient who suffered from hearing loss, was myopic from two and a half years of age, and needs to wear glasses." (PMID 34062854, 2021). "NT-3 delivery has been attempted in model animals with the aim of clinical treatment of hearing impairment, and it would be beneficial to further clarify the mechanism of Slitrk6 action in development of the inner ear and auditory signal processing." (PMID 21298075, 2011). "Thus, the involvement of functional deficits in SLITRK6 in human hereditary hearing impairment awaits further investigation." (PMID 21298075, 2011).
deafness (3 papers, 2021 to 2024). An inherited or acquired condition characterized by the complete loss of the ability to hear from one or both ears. "SLITRK6 regulates the outgrowth of sensory neurons in the inner ear and retina; its mutation may cause myopia and deafness." (PMID 36980855, 2023). "The pathogenic biallelic variants in the SLITRK6 gene cause deafness and myopia." (PMID 34062854, 2021).
Anxiety (2 papers, 2011 to 2022). Intense feelings of nervousness, tension, or panic often arise in response to interpersonal stresses. "Slitrk6 is significantly associated with Parkinson’s disease and bipolar disorder, as well as has significant associations with various psychiatric traits including anxiety, nervous feelings and alcohol dependence." (PMID 35456420, 2022). "Because Slitrk6-KO mice showed altered spontaneous activities in the three different contexts (home cage, and HB box), we evaluated whether these behavioral abnormalities were caused by elevated anxiety in a novel environment." (PMID 21298075, 2011).
bladder tumor (2 papers, 2018 to 2019). "SLIT and NTRK- like protein 6 (SLITRK6) is a known bladder tumor antigen, and is currently under investigation in clinical trials as a target for antibody-drug conjugate therapy." (PMID 31337362, 2019). "SLITRK6 is a member of the SLITRK family of neuronal transmembrane proteins that was discovered as a bladder tumor antigen using suppressive subtractive hybridization." (PMID 30361509, 2018).
upper tract urothelial carcinoma (2 papers, 2015 to 2024). "One gene highly over-expressed in upper tract urothelial carcinoma, SLITRK6, is the target of an antibody-drug conjugate currently being evaluated in phase I clinical trials." (PMID 26317352, 2015). "We also identify a marker, SLITRK6, as a potential target for patients with advanced upper tract urothelial carcinoma." (PMID 26317352, 2015). "One gene found to be over-expressed in upper tract urothelial carcinoma, SLITRK6, is an integral membrane protein known to have high levels of expression in certain carcinomas but low levels of expression in most other tissues." (PMID 26317352, 2015). "A study has demonstrated that both upper tract urothelial carcinoma (UTUC) and urinary bladder urothelial carcinoma (UBUC) have high SLITRK6 expression, rendering it a compelling therapeutic target for the management of UC." (PMID 38665947, 2024).
vestibular disorder (2 papers, 2011 to 2019). Pathological processes of the vestibular labyrinth which contains part of the balancing apparatus. "Other mouse models of vestibular disorder including Ames waltzer mice and Slitrk6-deficient mice have been used in previous studies." (PMID 31153359, 2019).
adenoma (1 paper, 2021). A neoplasm arising from the epithelium. "Statistically significant results include 6.20-fold downregulation of SLITRK6 (p = 0.010) in adenomas, and 3.22-fold upregulation of TCEA3 in adenomas with early carcinoma (p = 0.006)." (PMID 33670246, 2021). "A bioinformatics study on CRC showed differentially expressed SLITRK6 together with L1TD1 and ST6GALNAC1, and it was downregulated in CRC compared to adenomas using microarray expression analysis." (PMID 33670246, 2021).
breast tumours (1 paper, 2024). "Furthermore, 72 CSRs showed higher expression in breast tumours versus non-breast healthy tissues, including VTCN1 (log2FC = 7.0), LRRC (5.8), and SLITRK6 (5.5)." (PMID 38306344, 2024).
gastric cancer (1 paper, 2009). A primary or metastatic malignant neoplasm involving the stomach. "The gene SLITRK6 was selected as a candidate gene for both gastric cancer cell lines, however only in the GP202 gastric cancer cell line this gene was located in a deleted area." (PMID 19563644, 2009).
osteosarcoma (1 paper, 2022). A usually aggressive malignant bone-forming mesenchymal neoplasm, predominantly affecting adolescents and young adults. "Further validation of the gene expression profiles of these upregulated genes showed that PEDF was expressed in various osteosarcoma cell lines, whereas Slitrk6 protein was truncated in the SaOS-2 cell line." (PMID 35174090, 2022).
urothelial carcinoma (1 paper, 2015). A malignant neoplasm derived from the transitional epithelium of the urinary tract (urinary bladder, ureter, urethra, or renal pelvis). "An antibody to the SLITRK6 protein has been linked with a cytotoxic agent monomethyl auristatin E (AGS15E) and is currently in phase I clinical trials for patients with metatstatic urothelial carcinoma (protocol ID NCT 01963052)." (PMID 26317352, 2015).
cancer (4 papers, 2014 to 2022). A tumor composed of atypical neoplastic, often pleomorphic cells that invade other tissues. "SLITRK6, an integral membrane protein, has been found to be highly expressed in human adult neural stem-like cells and in several cancers." (PMID 33670246, 2021). "Many of these other potential enhancer-hijacking targets do not have well-established roles in cancer pathogenesis, however, we did notice a number of genes involved in cell adhesion (ALCAM, NCAM2, CADM2, and CDH9) and 2 SLIT and NTRK like family members (SLITRK1, SLITRK6)." (PMID 35538064, 2022).
tumor (4 papers, 2007 to 2025). "Interestingly, approximately 5% of tumor cells were negative for SLITRK6 expression, underlining the effect this ADC has on heterogenic cancers, which are typically found in patients." (PMID 34123841, 2021). "Utilizing tumor microarrays, SLIT and NTRK-like protein 6 (SLITRK6) were found to be expressed in 88% of bladder cancer specimens, of which 67% showed strong to moderate expression." (PMID 34123841, 2021). "Despite this evidence, it was observed that both SLITRK-6 negative tumor cells and cells expressing low levels of SLITRK6 respond to SV treatment." (PMID 35269424, 2022). "SLITRK6 expression is not homogeneous on tumor cells with 5% of cells negative for this protein." (PMID 35269424, 2022).
SLITRK6 also shares sentences with these, for which no sentence is quoted: lung carcinoma (3 papers); myopia (3); bladder cancer (2); Hearing impairment (2); alcohol dependence (1); bipolar disorder (1); CHARGE syndrome (1); colorectal (1); lung adenocarcinoma (1); Obesity (1); Parkinson disease (1); urinary bladder urothelial carcinoma (1); Usher syndrome (1); Visual impairment (1).